RN7SKP167 (RN7SK pseudogene 167)
Gene: Miscellaneous RNA gene on chromosome 10 (121,410,916 to 121,411,200, forward strand). Ensembl gene ENSG00000222979.
Homologues: Orthologues: chimpanzee 7SK (99% identical), guinea pig 7SK (63% identical). Paralogues in human: RN7SKP9 (78% identical), RN7SKP255 (77% identical), RN7SKP203 (77% identical), 7SK (76% identical), RN7SKP37 (76% identical), RN7SKP79 (76% identical), RN7SKP211 (76% identical), RN7SKP217 (76% identical), RN7SKP176 (75% identical), RN7SKP189 (75% identical), RN7SKP193 (75% identical), RN7SKP47 (75% identical), and 284 more.